CD36 (CD36 molecule (CD36 blood group))
Diseases named in the same sentence as CD36 in open-access papers (continued):
Sharing a sentence is not in itself a finding about the gene and the disease.
atherosclerosis (continued). "Our previous studies demonstrated that oxLDL binds to its receptor CD36, stimulating mitochondrial reactive oxygen species (mtROS), which are critical in atherosclerosis development." (PMID 40250804, 2025). "CD36 is a scavenger receptor that acts as a transporter of FAs and oxidized lipids, and plays a vital role in atherosclerosis and metabolic disorders." (PMID 39266539, 2024). "These cells subsequently bind to class A scavenger receptors (SR-A) and CD-36 to take up oxidized low-density lipoproteins (LDL) and release pro-inflammatory and pro-oxidant cytokines at inflammation sites, causing atherosclerosis." (PMID 39238504, 2024). "The role of CD36 in human atherosclerosis has been well studied and its relevance to human disease is not to be overlooked." (PMID 39705234, 2024). "The liver X receptor (LXR) and RXR heterodimer is another critical regulator of CD36 in macrophages, with significant implications for cholesterol metabolism, inflammatory responses and atherosclerosis." (PMID 39742252, 2024). "In atherosclerosis, in addition to fatty acids and cytokines, oxidized lipids, such as oxLDL, and cholesterol crystals drive CD36 expression." (PMID 39742252, 2024). "The binding and uptake of oxPAPC by CD36 on macrophages were demonstrated to activate signaling pathways that promoted foam cell formation during atherosclerosis." (PMID 39682740, 2024). "The entire process harnessed multiple machine learning algorithms to elucidate the fundamental signature genes intrinsic to atherosclerosis, ultimately pinpointing CD36, S100A10, and CSNK1A1 as genetically correlated markers." (PMID 39660117, 2024). "Given its role in phagocytosis, CD36 has garnered significant interest in studies focused on inflammation, atherosclerosis, and neurodegenerative diseases, among other areas." (PMID 39691192, 2024). "Phagocytosis of fat/lipids has also been indicated in other contexts, such as cancer, obesity, and atherosclerosis via a CD36-mediated mechanism." (PMID 39056808, 2024). "We and our colleagues have previously demonstrated a contributing role of CD36 in foam cell formation and the development of atherosclerosis." (PMID 39156133, 2024). "This research focused on improving atherosclerosis by modulating the PPARG/CD36 pathway in macrophages." (PMID 38468335, 2024). "In atherosclerosis, the expression levels of CD36, PPARG, MMP9 and SRC were upregulated, while NOB inhibited their expression." (PMID 38468335, 2024). "Earlier studies demonstrated CD36 as a receptor mediating binding and uptake of oxPAPC in macrophages, promoting foam cell formation during atherosclerosis." (PMID 39682740, 2024). "Conversely, USP14 deficiency regulates the posttranslational modifications of scavenger receptor CD36 to suppress atherosclerosis development and cardiac hypertrophy by regulating GSK-3β phosphorylation and mediates lipopolysaccharide-induced inflammation." (PMID 38909015, 2024). "We proceeded to examine the influence of nalmefene on oxLDL uptake by macrophages, given that nalmefene upregulates CD36 expression, which is crucial for incorporating oxLDL into macrophages and contributing to atherosclerosis development." (PMID 38560051, 2024). "Previously, CD36‐selective ligands have reduced macrophage accumulation in aortic lesions, diminished foam cell formation, and mitigated atherosclerosis progression in apoE‐null mice." (PMID 39552437, 2024). "Animal studies have highlighted the role of CD36 in cardiovascular diseases, particularly atherosclerosis and atherothrombosis." (PMID 39552437, 2024). "In summary, the pivotal involvement of the CD36-PPARγ pathway in atherosclerosis underscores its significance in both the prevention and treatment of atherosclerosis and its concomitant metabolic syndrome." (PMID 39660117, 2024).
atherosclerosis (continued). "Numerous studies have shown that CD36 participates in the development of atherosclerosis and that genetic deletion of CD36 or blocking of the CD36-induced signaling cascade decreases the formation of atherosclerotic lesions." (PMID 38218337, 2024). "Nevertheless, our findings are consistent with these studies showing low levels of CD36 in peripheral blood monocytes in patients with rheumatoid arthritis and subclinical atherosclerosis and children with chronic kidney disease." (PMID 39524404, 2024). "EDP activities impact the course of atherosclerosis through regulating the levels of the sialylation of CD36, a process largely governed by the ERC and its catalytic subunit, NEU1, to modulate oxLDL uptake in these cells." (PMID 39194692, 2024). "Not only does oxLDL drive an increase CD36 expression, it also contributes to the reprogramming of macrophages in atherosclerosis." (PMID 39742252, 2024). "CD36 has been observed to be associated with the activation of the NLRP3 and induce atherosclerosis formation." (PMID 39039680, 2024). "Accumulation of oxLDL in macrophages is a sign of early atherosclerosis as it binds to scavenger receptors such as CD36 and oxLDL." (PMID 39463572, 2024). "USP14 depletion was demonstrated to restrain foam cell formation through inhibiting CD36-mediated lipid uptake, which is considered as a therapeutic strategy for atherosclerosis." (PMID 38424494, 2024). "Drugs targeting the PPARG/CD36 signaling pathway are promising therapeutic options for the therapy of atherosclerosis." (PMID 38468335, 2024). "A significant amount of foam cells are formed in vitro and in vivo due to CD36 and blocking CD36 expression or downstream signaling prevents animals from absorbing ox-LDL which limits the progression of experimental atherosclerosis in mice." (PMID 38881887, 2024). "Derivatives of 2-(2-phenylethyl) chromone have been shown to mitigate the expression of CD36 in macrophages mediated by endoplasmic reticulum stress, thereby inhibiting the formation of foam cells and exerting a therapeutic effect on atherosclerosis." (PMID 39323637, 2024). "CD36 plays a major role in binding and uptake of oxLDL during lipid‐laden foam cell formation, a critical process in atherosclerosis." (PMID 38494843, 2024). "CD36 is a macrophage scavenger receptor that can bind and uptake oxLDL, leading to foam cell formation and the exacerbation of atherosclerosis." (PMID 39528464, 2024). "Recent studies have demonstrated that CD36 triggers the NLRP3 inflammasome in atherosclerosis, while inhibition of CD36 suppresses NLRP3 inflammasome activation." (PMID 38572426, 2024). "Previously, others and we have shown a role for CD36 in oxLDL uptake by macrophages and SMCs leading to foam cell formation and atherosclerosis." (PMID 38537695, 2024). "Accumulating studies have revealed that CD36 plays vital parts in inflammation and metabolic diseases, including nonalcoholic steatohepatitis, atherosclerosis, diabetes, and cancer." (PMID 39524404, 2024). "CD36 cell membrane expression was greatly increased and shown to be essential to the increase in atherosclerosis, macrophage and necrotic core areas in vivo." (PMID 39742252, 2024). "In summary, our study highlights monocyte infiltration as a crucial contributor to atherosclerosis development, with CD36, S100A10, and CSNK1A1 emerging as prominent biomarkers for disease detection." (PMID 39660117, 2024). "On the other hand, oxLDL regulates the expression of dipeptidyl dipeptidase IV (DPP4) in macrophages, leading to an increase in CD36+ cells, which contributes to the inflammatory processes of atherosclerosis in obese and insulin-resistant patients." (PMID 39027472, 2024). "Transaldolase upregulates GSH production, thereby suppressing p38 activity and reducing the CD36 level, ultimately preventing foam cell formation and atherosclerosis." (PMID 37528662, 2023).
atherosclerosis (continued). "Considering all these results, it is thought that thedeveloped immunosensor has application potential for rapid minimal-invasivedetection of CD36, which is a biomarker for atherosclerosis, prediabetes,and DM in clinical analysis." (PMID 36816687, 2023). "In conclusion, MMP9, MMP12, FABP4, and CD36 genes are closely related to the occurrence and development of atherosclerosis and NSCLC." (PMID 37978381, 2023). "Experiments performed in Cd36-/- animals confirmed that CD36 upregulation was involved in the acceleration of atherosclerosis in Card9-/- animals." (PMID 37528097, 2023). "On the contrary, CD36 functions together with other cell surface proteins in efferocytosis to mitigate inflammation and to promote the resolution of atherosclerosis." (PMID 37332345, 2023). "7-HF has also been studied to inhibit the accumulation of lipids in high glucose-induced macrophage cells of an in vitro model of atherosclerosis by suppressing the protein expression of CD36." (PMID 37760913, 2023). "CD36 is involved in angiogenesis, lipid metabolism, atherosclerosis, inflammation, phagocytosis, and clearing apoptotic cells." (PMID 36759676, 2023). "Given the roles of CD36 in the etiology of metabolic disorders, such as atherosclerosis, diabetes, and non-alcoholic fatty liver disease, the clinical implications of CD36-targeted therapy are wide-reaching, even beyond cancer." (PMID 37371076, 2023). "Recently, we demonstrated that the deletion of macrophage NCOR1 aggravates atherosclerosis by promoting CD36-triggered foam cell formation via PPARG derepression." (PMID 37349757, 2023). "A hallmark of the development of atherosclerosis is the uptake of modified LDL, which undergoes spontaneous oxidation or modification, by macrophages via scavenger receptors such as CD36 or SR-A, resulting in the formation of foam cells." (PMID 36598592, 2023). "Lastly, EP80317 is a synthetic peptide ligand of CD36 that has been shown to mitigate the development of hypercholesterolemia and atherosclerosis in mice." (PMID 37371076, 2023). "CD36 has important roles in metabolic diseases, including atherosclerosis, NAFLD,35, 36, 37 obesity, chronic metabolic inflammation, and diabetes mellitus, as well as hyperlipidemia, through binding with multiple ligands." (PMID 40625574, 2023). "Based on the known role of CD36 in macrophage foam cell formation in the context of atherosclerosis, we next investigated the effects of oxPL on CD36-mediated lung macrophage accumulation and phenotype." (PMID 38098035, 2023). "CD36 has an important role in endothelial cells, smooth muscle cells, monocytes, macrophages, and platelets in the development of atherosclerosis." (PMID 40625574, 2023). "CHI3L1, CD36, IL-18, and RARRES2 genes have also been reported to be associated with IR, whereas APOA1, CD36, LEP, FN1, and CETP genes were found to be associated with atherosclerosis." (PMID 36984867, 2023). "Kaempferol possessed an inhibitory effect on the expression of oxidized low-density lipoprotein (oxLDL) and the development of atherosclerosis, as well as an inhibitory effect on macrophage activation via CD36 inhibition." (PMID 37064204, 2023). "CD36 has been previously evaluated as a therapeutic target in diseases other than cancer, such as atherosclerosis, non-alcoholic fatty liver disease, and diabetes." (PMID 37371076, 2023). "CD36 on monocytes/macrophages has been identified as an important factor in atherosclerosis through binding and promoting endocytosis of ox-LDL." (PMID 37228156, 2023). "A recent study in atherosclerosis demonstrated that the overexpression of IGF2 enhances oxidized low-density lipoprotein-induced CD36 expression, resulting in increased lipid accumulation in human THP-1 macrophages." (PMID 37107630, 2023). "We identified 15 identical pathogenic genes, and four of which (MMP9, MMP12, CD36, and FABP4) were considered as the key target genes of atorvastatin in anti-atherosclerosis and NSCLC." (PMID 37978381, 2023).
atherosclerosis (continued). "CD36 expressed by macrophages promotes the inflammatory response and the formation of foam cells leading to the development of atherosclerosis." (PMID 38196515, 2023). "We demonstrate that SFN can play a preventive role in macrophage foam cell formation and atherosclerosis through restraining cholesterol uptake and inducing efflux via the potential modulation of the expression of CD36, ABCA1/G1, PPARγ and Nrf2/HO-1." (PMID 37432260, 2023). "The increased serum concentration of CD36 is significantlyassociatedwith atherosclerosis, insulin resistance, and diabetes mellitus." (PMID 36816687, 2023). "In summary, CARD9 is a key protective pathway in atherosclerosis, modulating macrophage CD36-dependent inflammatory responses, lipid uptake and autophagy." (PMID 37528097, 2023). "According to Silverstein and Febbraio (2009), CD36 is related to the pathogenesis of diseases such as atherosclerosis and Alzheimer’s disease." (PMID 36816031, 2023). "TRPM2 deletions protects against atherosclerosis by suppresses the activation of the CD36 signaling." (PMID 37588590, 2023). "In cardiovascular disease, reports demonstrated an important role for CD36 signaling through Lyn kinase in establishing a foam cell phenotype in the context of atherosclerosis." (PMID 38098035, 2023). "In models of atherosclerosis, suppression of CD36 transcription, function, or increased CD36 degradation were associated with a reduction in foam cell formation and reduced uptake of oxidized lipids by macrophages." (PMID 35991116, 2022). "As a recognition receptor, CD36 interacts with oxLDL, recruits macrophages to the intima, inhibits macrophage migration, and plays an important role in atherosclerosis." (PMID 36325361, 2022). "We previously demonstrated that activation of PXR by other ligands including BPA and PCN increased CD36 expression and lipid accumulation in macrophages of ApoE−/− mice in vivo, likely contributing to the increased atherosclerosis in those mice." (PMID 35406689, 2022). "Macrophage CD36 can interact with oxidized low-density lipoprotein (oxLDL), trigger signaling cascades for inflammatory response, and is involved in atherosclerosis." (PMID 35693817, 2022). "The significantly expressed and atherosclerosis-associated genes (MSR1, CD36, NR1H3) were detected by transcriptome analysis." (PMID 36613720, 2022). "Nrf2 knockout approach revealed that Nrf2 upregulates the expression of receptor CD36 and enhances uptake of oxLDL and foam cell formation in macrophages, thereby promoting atherosclerosis development." (PMID 36231004, 2022). "Several studies have demonstrated that protein expression changes in macrophages affect atherosclerosis, such as CD36 and FABP." (PMID 34980145, 2022). "Nrf2 upregulates CD36 thereby promoting foam cell formation and the pathogenesis of atherosclerosis." (PMID 36231004, 2022). "CD36 is also a worthwhile target for further investigation in the treatment of cardiovascular disease, as CD36 low molecular weight inhibitors reduced both atherosclerosis and metabolic abnormalities in a leptin and LDL receptor double knockout mouse model." (PMID 36551839, 2022). "The scavenger receptor CD36 is a key macrophage receptor facilitating ox-LDL uptake and foam cell formation, and studies investigating CD36 deletion in atherosclerosis-prone mice demonstrate that macrophages displayed decreased proinflammatory characteristics." (PMID 35758143, 2022).
atherosclerosis (continued). "In atherosclerosis, PPARγ is reported to bind with the promoter region of CD36, and the PPARγ agonist BLR49653 strongly induces CD36 expression." (PMID 35432274, 2022). "In a hyperlipidemic ApoE−/− model of atherosclerosis CD36 was shown to trigger TLR4-TLR6 dependent accumulation of TRIF-dependent chemokine RANTES and an overall increase in ROS production by macrophages." (PMID 35237675, 2022). "CD36 plays an important role in lipid accumulation, inflammatory injury, apoptosis, and oxidative stress, and is a core factor in the initiation of atherosclerosis, diabetes, non-alcoholic fatty liver disease, and other diseases." (PMID 36611964, 2022). "Previous experiments have shown that disruption of the SRA1 or CD36 pathway partially inhibits the uptake of acetylated-LDL (Ac-LDL) or ox-LDL by macrophages while delaying the progression of atherosclerosis in hypercholesterolemic mice." (PMID 35966555, 2022). "For example, some studies suggested that Cd36 is involved in fatty acid uptake, apoptosis, angiogenesis, phagocytosis, inflammation and atherosclerosis." (PMID 36157062, 2022). "When the expression of CD36 was inhibited, cholesterol uptake was significantly reduced and the symptoms of atherosclerosis were alleviated." (PMID 35399657, 2022). "In this review, we focus on how the dual functions of CD36 as a fatty acid transporter and cell signaling receptor control immune cell fate and how this impacts disease progression in cancer and atherosclerosis." (PMID 35438721, 2022). "For instance, in atherosclerosis, Nrf2 upregulation promotes CD36 transcription in macrophages, inducing free cholesterol accumulation, which later leads to the formation of foam cells, highly toxic to the cells." (PMID 36290577, 2022). "Recent studies demonstrated that CD36 is involved in inflammation, angiogenesis, lipid metabolism and atherosclerosis progression." (PMID 35237675, 2022). "On macrophages infiltrating the arterial intima, CD36 acts as a scavenger receptor to internalize oxidized low-density lipoproteins, which induce the secretion of inflammatory cytokines and promote atherosclerosis." (PMID 35299232, 2022). "Our previous study reported that TSD had a positive role in anti-atherosclerosis by upregulating the activity of CD36 and lysosomal integral membrane protein II analogous-1 (CLA-1), which is important in cholesterol efflux." (PMID 36362263, 2022). "CD36 is decreased in pathological cardiac hypertrophy and increased in diabetic cardiomyopathy and atherosclerosis." (PMID 35396566, 2022). "TMAO furtherpromotes atherosclerosis by activating the CD36-dependent MAPK/Janus kinases(JAKs) pathway and triggering the expression of VCAM-1, TNF-α andIL-1β via the NF-κB pathway." (PMID 39077721, 2022). "Its expression along with its dual functions in both innate and adaptive immune cells contribute to pathogenesis of common diseases, including atherosclerosis and tumor progression, which makes CD36 and its downstream effectors potential therapeutic targets." (PMID 35438721, 2022). "Expression of CD36 in macrophages and atherosclerosis: the role of lipid regulation of PPARgamma signaling." (PMID 35703653, 2022). "We and others have shown that CD36 plays a role in obesity, atherosclerosis, and insulin resistance by both uptake of ligands and promotion of inflammatory signaling pathways, with the resultant secretion of reactive oxygen species and cytokines." (PMID 34888367, 2021). "OxLDL is a ligand for PPARγ and upregulates the expression of CD36, favoring the uptake of OxLDL to macrophages and consequently contributing to the development of atherosclerosis through immune system activation." (PMID 34204618, 2021). "CD36 is a key mediator of macrophage phagocytosis of oxidized low-density lipoprotein (oxLDL) in atherosclerosis." (PMID 34803512, 2021).